IGFBP2 (insulin like growth factor binding protein 2)
Diseases named in the same sentence as IGFBP2 in open-access papers (continued):
Sharing a sentence is not in itself a finding about the gene and the disease.
breast carcinoma (continued). "In addition to these studies, a survival study amongst women with postmenopausal breast cancer found that relatively high serum IGFBP-2 levels were associated with increased survival and also found evidence of effect modification by BMI." (PMID 26106415, 2015). "Nevertheless, given the association between AH and breast cancer, if our finding that serum IGFBP-2 level is associated with reduced risk of AH is confirmed in further studies, this may suggest a role for IGFBP-2 in the early stages of breast carcinogenesis." (PMID 26106415, 2015). "Hyperinsulinemia reduces hepatic synthesis of IGFBP-1 and IGFBP-2, thereby indirectly enhancing this signaling pathway and activating multiple classical oncogenic pathways, ultimately accelerating breast cancer progression." (PMID 41310487, 2025). "For example, research on breast cancer reported that the expression levels of IGFBP2 were substantially elevated in the T1 stage of breast cancer compared to benign lesions." (PMID 40728947, 2025). "This suggests that IGFBP2 can potentially facilitate metastatic development and serve as a critical biomarker for predicting lymph node metastasis in breast cancer." (PMID 40728947, 2025). "Numerous studies focusing on breast cancer cells have demonstrated that increased IGFBP-2 levels can intrinsically stimulate cancer cell proliferation and confer resistance to treatment." (PMID 38893232, 2024). "The role if insulin-like growth factor binding protein-2 (IGFBP-2) in mediating chemoresistance in breast cancer cells has been demonstrated, but the mechanism of action is unclear." (PMID 38893232, 2024). "WOKVAC is a plasmid-based DNA vaccine encoding epitopes from three breast cancer antigens: HER2, IGFBP2, and IGF1R." (PMID 38256137, 2024). "Studies showed that adipose tissue near breast cancer secreted IGFBP2 (Insulin-like Growth Factor Binding Protein 2), which affected IGF-II autocrine signaling in cancer cells, thereby inhibiting the progression of breast cancer." (PMID 39867555, 2024). "We previously showed that IGFBP-2 contributes to chemoresistance in both prostate and breast cancer cells, but the mechanism was unclear." (PMID 38893232, 2024). "Cancer-associated adipocytes (CAAs) produce elevated insulin-like growth factor binding protein 2 (IGFBP-2) levels in the tumor microenvironment, which upregulates MMP-2 and then promotes migration, invasion, and metastasis in breast cancer." (PMID 36670988, 2023). "Adipocyte-derived IGFBP2 from healthy stroma effectively limits IGF-II-driven breast cancer progression." (PMID 37436978, 2023). "Here we show that healthy mammary adipocytes are able to restrain breast cancer invasion through secretion of IGFBP2, a novel anti-invasive adipocrine factor." (PMID 37436978, 2023). "Our experiments demonstrate that a healthy human mammary gland is rich in IGFBP2-expressing adipocytes and that IGFBP2 secreted by normal tissue-derived adipocytes efficiently blocks breast cancer invasion." (PMID 37436978, 2023). "In line with this role, adipocytes differentiated from patient-derived stromal cells were found to secrete IGFBP2, which significantly inhibited breast cancer invasion." (PMID 37436978, 2023). "We further demonstrated that plasma levels of CCL28 and IGFBP2 proteins were significantly higher in breast cancer patients during taxane-based chemotherapy than post-chemotherapy." (PMID 38093346, 2023). "Meanwhile, IGFBP-2 secreted by mature adipocytes greatly affected the metastatic capability of breast cancer cells." (PMID 35701840, 2022).
breast carcinoma (continued). "The IGFBP-2 protein level in adipocytes was higher in adjacent peritumoral metastatic breast cancer tissues, compared to that in metastatic tissues." (PMID 35701840, 2022). "The anti-tumor effect of peptide immunization targeting IGFBP-2 in mice challenged with a mammary cancer cell line was also dependent on CD8+ T-cells." (PMID 34526999, 2021). "On the other hand, silencing of IGFBP-2 suppressed MCF7 breast cancer cell proliferation and increased cell death, suggesting IGFBP-2 as promoter of breast cancer survival." (PMID 31620367, 2019). "Similar anti-proliferative effects of IGFBP-2 were reported in a human breast cancer cell line, Hs578T and in human embryonic kidney fibroblasts." (PMID 31903164, 2019). "We measured IGF‐I, IGF‐II, pro‐IGF‐II, IGF bioactivity, IGFBP‐2, ‐3, and pregnancy‐associated plasma protein A (PAPP‐A), an IGFBP regulator, in baseline samples of 301 women with breast cancer treated on four protocols (Odense, Denmark: 1993–1998)." (PMID 29722920, 2018). "Obviously, the present study does not allow us to draw such conclusions, but we do believe it is possible to justify the idea that PAPP‐A and IGFBP‐2 are involved in breast cancer." (PMID 29722920, 2018). "Knockdown of IGFBP-2 blocks cell proliferation and increases the death of breast cancer MCF-7 cells." (PMID 28410230, 2017). "We have shown that hyperglycaemia induces resistance to chemotherapy through upregulation of fatty acid synthase (FASN) in breast cancer cells and increased insulin-like binding protein 2 (IGFBP-2) in prostate cancer cells." (PMID 29088813, 2017). "Silencing the expression of IGFBP-2 using siRNA negated the hyperglycaemia-induced chemo-resistance and restored the sensitivity of breast cancer cells to doxorubicin in high glucose." (PMID 29088813, 2017). "The overexpression of IGFBP2 has been reported to be responsible for tamoxifen resistance and recurrence in pre-menopausal women with ERα-positive breast cancer." (PMID 28903396, 2017). "Recently, IGFBP2 has been identified as a potential and valuable biomarker in malignancies including breast cancer, ovarian cancer, colorectal cancer, glioblastoma, lung cancer, prostate cancer, and gastric cancer." (PMID 28410230, 2017). "Here, we investigated the effect of hypoxia on IGFBP-2 in breast cancer cells and how this affected chemo-sensitivity in euglycaemic and hyperglycaemic conditions." (PMID 29088813, 2017). "High glucose increased the abundance and expression of IGFBP-2 in breast cancer cells that led to reduced sensitivity to chemotherapy." (PMID 29088813, 2017). "Having established that hypoxia reduced the abundance of IGFBP-2, we further investigated the effect of this hypoxia-induced reduction in IGFBP-2 on the response of breast cancer cells to chemotherapy." (PMID 29088813, 2017). "Foulstone and coworkers found that IGFBP‐2 controls estrogen receptor alpha expression in breast cancer cells." (PMID 26507795, 2016). "Taken together, these data suggest that the co-culture of breast cancer cells with adipocytes induces the production of IGFBP-2 by adipocytes, which then stimulates the invasion of breast cancer cells." (PMID 25747684, 2015). "According to previous studies, IGFBP-2 facilitates the migration of breast cancer cells in response to IGF signaling, and exogenous IGFBP-2 reduces phosphatase and tensin homolog deleted from chromosome 10 (PTEN) levels to protect MCF-7 cells against death." (PMID 25747684, 2015). "Breast cancer-specific survival was shorter for Native Hawaiians with IGFBP2-positive compared to those with IGFPB2-negative tumors (Log-rank P = 0.02)." (PMID 25619494, 2015).
breast carcinoma (continued). "Findings from our study and from these previous studies in breast cancer are in contrast with previous experimental evidence suggesting that IGFBP-2 promotes cell proliferation and tumor growth." (PMID 26106415, 2015). "Specifically, the interaction of human breast carcinoma cells with mature human adipocytes induces the aberrant secretion of active IGFBP-2 by the adipocytes." (PMID 25747684, 2015). "IGFBP-2 secreted by mature adipocytes plays a key role in promoting the metastatic ability of MCF-7 breast cancer cells." (PMID 25747684, 2015). "We analyzed by immunohistochemistry the presence of MMP-2 in tumor cells and IGFBP-2 in the adipocytes around tumor cells in samples of human ductal infiltrant mammary tumors." (PMID 25747684, 2015). "It has been reported that exogenous IGFBP-2 promotes proliferation and/or invasion of many cancer cells, including epithelial ovarian carcinoma cells, breast cancer cells and neuroblastoma cells." (PMID 24690948, 2014). "We recently showed that IGFBP-2 is a novel positive regulator of the ERα and that this promotes cell survival in ERα-positive breast cancer cells." (PMID 24847310, 2014). "Nevertheless, secretion of IGFBP-2 was lower in ER-negative breast cancer cells compared to ER-positive cells indicating a positive or at least a permissive effect of ER on IGFBP-2 expression in mammary cells." (PMID 24778626, 2014). "It will be interesting to investigate further the role of EGCG-induced changes of IGFBP-2 in breast cancer." (PMID 24847310, 2014). "IGFBP2, which was measured in the current study, has been reported to act as a potent mitogenic, by enhancing the proliferative capacity of breast cancer cells, protecting them from chemotherapy-induced apoptosis, and maintaining estrogen-receptor expression." (PMID 24637962, 2014). "In the present study, to elucidate the cellular pathways influenced by IGFBP2 in breast cancer, gene expression profiling of IGFBP2 knockdown breast cancer cells was compared with the expression profile of IGFBP2 positive breast tumors." (PMID 23767917, 2013). "Since the previous results showed an increase in β-catenin expression upon IGFBP2 over expression, we sought to examine the correlation of β-catenin and IGFBP2 staining in human breast cancer tissues." (PMID 23767917, 2013). "IGFBP2 correlation with proliferation has been studied extensively in several tumor cells including in breast cancer cells." (PMID 23767917, 2013). "Knockdown of IGFBP2 in BT474 breast cancer cells substantially decreased the expression of β-catenin in both the clones C5 and C12, suggesting a direct regulation of β-catenin by IGFBP2." (PMID 23767917, 2013). "Knockdown of IGFBP2 resulted in differential expression of 2067 up regulated and 2002 down regulated genes in breast cancer cells." (PMID 23767917, 2013). "The cell-autonomous effect of IGFBP2 in leukemia cells is also different from the extrinsic effect of IGFBP2 in supporting survival of certain solid cancer cells such as breast cancer cells." (PMID 24191913, 2013). "While IGFBP2 has cell-autonomous effect to support growth of leukemia cells, the extrinsic IGFBP2 stimulates the activity of HSCs and some other cancer cells such as breast cancer cells." (PMID 24191913, 2013). "This study investigates the molecular targets and biological pathways targeted by IGFBP2 in breast cancer." (PMID 23767917, 2013). "In the previous experiments, we identified genes differentially expressed in breast tumors and breast cancer cells lines based on IGFBP2 expression." (PMID 23767917, 2013). "This study highlights regulation of β-catenin by IGFBP2 in breast cancer cells and most importantly, combined expression of IGFBP2 and β-catenin is associated with lymph node metastasis of breast tumors." (PMID 23767917, 2013).
breast carcinoma (continued). "Our data on the regulation of different pathways such as MAPK, Cell cycle, Focal adhesion and Wnt corroborate the reported functional significance of IGFBP2 with respect to its pro proliferative and tumor promoting roles in breast cancer cells." (PMID 23767917, 2013). "In view of the pro-tumorigenic actions of IGFBP2 reported in several cancers including breast tumors, we decided to delineate the molecular mechanism of IGFBP2 actions in breast cancers." (PMID 23767917, 2013). "Taken together, the data from the IGFBP2 knockdown cells and IGFBP2 positive breast tumors suggest a positive correlation of IGFBP2 with pro-tumorigenic pathways including Wnt pathway in breast cancer." (PMID 23767917, 2013). "In breast cancer, IGFBP2 over expression has been shown to confer drug resistance and increased expression has been reported to correlate with lymph node metastasis In T1 breast carcinomas." (PMID 23767917, 2013). "It has been shown that IGFBP-2 is able to exert intrinsic effects on a Ewing sarcoma, and on a breast cancer, cell line by binding to cell surfaces through its RGD recognition sequence." (PMID 21487405, 2011). "We recently identified IGFBP-2 as a novel regulator of PTEN in breast cancer cells via its interaction with integrin receptors although in those cells the abundance of PTEN protein was reduced." (PMID 21487405, 2011). "Igfbp2 expression was significantly higher in breast cancer tissue compared with benign breast tissue and Igfbp2 inhibition attenuated the associated aggressive phenotype of breast cancer cells both in vitro and in vivo." (PMID 20808936, 2010). "It seems, however, that AAbs to IGFBP-2 have little value for screening and early diagnosis of breast carcinoma when examined alone." (PMID 21113302, 2010). "In a study of African Americans, with replication in Nigerians, we reported significant associations of SNPs within the IGFBP2 to IGFPB5 region and the risk of breast cancer." (PMID 19843326, 2009). "Two hundred samples from healthy volunteers, 80 samples from breast cancer patients, and 80 samples from colon cancer patients were assayed for antibodies to IGFBP-2 using the capture ELISA." (PMID 18510754, 2008). "Levels of IGFBP-2 antibodies were increased in breast cancer patients compared to normal volunteers (p = 0.013), and in colon cancer patients compared to normal volunteers (p < 0.001) when analyzed by Mann-Whitney U test." (PMID 18510754, 2008). "IHC of tissue microassays confirms a tumour-specific upregulation of IGFBP-5 and IGFBP-2 in primary breast cancers and their lymph node metastases." (PMID 15642160, 2005). "Breast cancer cells typically express several IGFBPs, with IGFBP-2, IGFBP-3, IGFBP-4 and IGFBP-5 being observed most often." (PMID 15642160, 2005). "Finally, hyperglycemia influences the chemoresistance in various cancers via multiple modalities, such as the upregulation of insulin-like growth factor binding protein-2 (IGFBP-2) in breast cancer and the SMAD3 and MYC phosphorylation in colorectal cancer." (PMID 40266540, 2025). "LncRNA KB-1980E6.3 maintains the stemness of breast cancer stem cells by interacting with IGFBP2." (PMID 35470736, 2022). "However, various studies have clarified that the overexpression of IGFBP2 are related to poorer prognosis in breast cancer, endometrial cancer, colorectal cancer, pancreatic ductal adenocarcinoma, lung cancer, and glioblastoma." (PMID 33282953, 2020). "Many studies support that IGFBP‐2 expression plays an oncogenic role in breast cancer." (PMID 29722920, 2018). "PI3K/Akt signalling pathway plays a fundamental role in IGFBP-2 stimulation in breast cancer." (PMID 29088813, 2017).
breast carcinoma (continued). "This glucose mediated regulation of IGFBP-2, however, was different in breast cancer cells." (PMID 29088813, 2017). "IGFBP2, having been widely accepted as one of the estrogen-responsive genes, appears to be involved in the maintenance of ERα and is regulated by E2 administration in ERα-positive breast carcinoma cell lines, rat hippocampus and adult articular cartilage." (PMID 28410230, 2017). "Understanding the role of FASN and IGFBP-2 in chemo-resistance could provide a novel target for improving the effectiveness of breast cancer treatment." (PMID 29088813, 2017). "Also, in breast cancer, IGFBP‐2 exerts malignant potential, and again, this depends on the RGD‐motif but involves regulation of estrogen receptors as demonstrated by the Perks laboratory." (PMID 26507795, 2016). "All of this evidence supports the concept that IGFBP-2 secreted from human adipocytes may promote breast cancer cell metastasis." (PMID 25747684, 2015). "Estrogen receptor (ER) status directly correlates with IGFBP2 expression in breast cancer, with ER-positive cancers having higher levels of IGFBP2 than ER-negative cancers, and therefore the high levels of IGFBP2 may simply reflect a functional ER pathway." (PMID 25774149, 2015). "Thus, serum level of IGFBP-2 is a plausible marker for the progression from benign proliferative breast disease to proliferative disease with AH and ultimately to breast cancer." (PMID 26106415, 2015). "Additional clinical trials are utilizing IGFBP2 as a potential immunotherapy target (NCT00821964) as well as a marker for cancer risk (NCT02450097), for colorectal cancer survival (NCT00503685) and for monitoring breast cancer treatment response (NCT01293032)." (PMID 26317790, 2015). "We examined the expression profiles of the IGF1, IGF1R, IGFBP2 (IGF-binding proteins), and IGFBP3 proteins in breast tumor tissue and their relationships with all-cause and breast cancer-specific survival up to 17 years postdiagnosis in a multiethnic series of 358 patients in Hawaii, USA." (PMID 25619494, 2015). "However, in other breast cancer cell lines IGFBP-2 acts as a survival factor, enhancing proliferative potential and protecting cells against chemotherapy-induced death." (PMID 26106415, 2015). "In addition, we found that the IGFBP-2 secreted by adipocytes is mainly responsible for the increased invasion ability of breast cancer cells." (PMID 25747684, 2015). "In our study, the human adipokine chip test of the co-culture supernatant of MCF-7 cells and adipocytes revealed some altered proteins which are reported to be involved in the regulation of proliferation and metastasis of breast cancer cells, such as IGFBP-2, IL-6sR, IL-8, leptin, MIF, and TGF-β." (PMID 25747684, 2015). "In some specific breast cancer cell lines IGFBP-2 has a proapoptotic effect." (PMID 26106415, 2015). "In another study, we have found that enough exogenous IGFBP-2 could stimulate endogenous IGFBP-2 expression in four breast cancer cells and different cell lines had different basal IGFBP-2 expression (data was not shown)." (PMID 25747684, 2015). "Therefore, similar to cells from the brain a synergistic effect of E2 and P4 on IGFBP-2 secretion was found in breast cancer explants." (PMID 24778626, 2014). "Furthermore, IGFBP-2 is highly expressed by antiestrogen-resistant breast cancer cell lines and in antiestrogen-resistant RU58R-1 cells, IGFBP-2 expression was suppressed by E2 but massively stimulated by pure antiestrogen." (PMID 24778626, 2014). "This study highlights the pathways and genes regulated by IGFBP2 in breast cancer." (PMID 23767917, 2013). "Though implicated in the progression of breast cancer, the molecular mechanisms involved in IGFBP2 actions are not well defined." (PMID 23767917, 2013). "IGFBP5 and IGFBP2 are overexpressed in breast cancer tissues, and are involved in apoptosis." (PMID 19843326, 2009).